NOX4 (NADPH oxidase 4)
Diseases named in the same sentence as NOX4 in open-access papers (continued):
Sharing a sentence is not in itself a finding about the gene and the disease.
asthma (continued). "In addition to the role of Duox in asthma, Nox4 was also identified to express along with Duox1 and Duox2 in bronchial biopsy specimens by using microarray." (PMID 29257052, 2017). "Given the fact that the ASM cell layer is thickened in asthma, it may imply that NOX4 also plays a role in ASM hyperplasia and hypertrophy in the lungs of other chronic pulmonary diseases." (PMID 27656649, 2016). "In addition, we have previously reported that NOX4 expression was increased in airway smooth muscle in asthma, leading to increased ROS production and intrinsic airway smooth muscle hypercontractility." (PMID 26836936, 2016). "Several chemicals have been found to reduce ASM gel contraction in vitro including inhibitors of phospholipase C, myosin light chain kinase, Rho kinase, and NOX4 and thus this has identified these enzymes as potential targets for future novel asthma treatments." (PMID 23577039, 2013). "This could be especially important given that β2AR agonism itself generates ROS in the airway epithelium, and also since the asthma-disease state is characterized by heightened level of ROS, including NOX4 upregulation in both airway epithelial cells and the underlying smooth muscle." (PMID 37865997, 2023). "Moreover, NOX4-generated ROS may mediate airway smooth muscle hypercontractility in asthma patients and alveolar capillary barrier dysfunction in patients with hyperoxia-induced lung injury." (PMID 30669315, 2019). "Our findings suggest that TRPV4 integrates TGFβ1 and ROS signaling through NOX4 and, TRPV4-NOX4 interaction is amenable to target lung remodeling during asthma." (PMID 32555397, 2020). "Given that NOX4 can regulate the expression of ROS, NOX4 may also be involved in regulating NLRP3 activation in asthma." (PMID 35711428, 2022). "To understand the significance of the TRPV4-NOX pathway in fibroblast differentiation in asthma, we took advantage of fibroblasts isolated from normal (NHLF) and from patient suffering from asthma exacerbation (DHLF) and analyzed NOX4 expression in both cell types." (PMID 32555397, 2020). "Indeed, both the NOX4 mRNA and protein expression levels were increased in OVA/LPS-induced asthma and reversed by IC87114 treatment." (PMID 29504610, 2018). "Pharmacologic inhibition of Nox4 improved ciliary function in ex vivo epithelial strips and abolished ciliary abolished ciliary dysfunction in the murine asthma model with no reduction in inflammation." (PMID 29257052, 2017). "Levels of 8-oxo-dG and NOX4 were elevated in patients with neutrophilic vs nonneutrophilic asthma, DUOX1 was elevated in both, and DUOX2 was elevated in nonneutrophilic asthma in vivo." (PMID 26836936, 2016). "NOX4 and DUOX1/2 expression in the epithelium was evident in asthma." (PMID 26836936, 2016). "Nox4 and Duox1 were both elevated and Duox2 was elevated in nonneutrophilic asthma." (PMID 29257052, 2017). "In contrast to DUOX1, which was increased in asthma independent of inflammatory phenotype, and DUOX2, which was only increased in nonneutrophilic asthma, NOX4 expression was upregulated only in the bronchial epithelium from patients with asthma with neutrophilic inflammation in vivo." (PMID 26836936, 2016). "NOX4 and DOUX1 levels in the neutrophilic murine model of asthma are elevated, whereas only DOUX2 is elevated in the non-neutrophilic murine model of asthma." (PMID 35796922, 2022). "Gene array analysis revealed the presence of NOX4 and DUOX1 and DUOX2 expression, but not the other NOX family members, in primary basal epithelial cells from ≥ 3 of the six donors with asthma." (PMID 26836936, 2016). "NOX4 mRNA in epithelial ALI cultures was significantly increased in neutrophilic asthma samples compared with healthy control samples (P = .009) and nonneutrophilic asthma samples (P = .0061) (ANOVA, P = .004)." (PMID 26836936, 2016).
idiopathic pulmonary fibrosis (18 papers, 2013 to 2024). Idiopathic pulmonary fibrosis (IPF) is a nonneoplastic pulmonary disease that is characterized by the formation of scar tissue within the lungs in the absence of any known cause. "Notably, the NOX1/NOX4 dual inhibitor GKT137831 is the only NOX inhibitor that has entered clinical trials [GKT137831 in IPF Patients with Idiopathic Pulmonary Fibrosis (GKT137831), NCT03865927]." (PMID 32605023, 2020).
kidney damage (18 papers, 2011 to 2025). "It has been shown that although glomerular Nox4 expression can be increased in some nephropathies, the loss of tubular Nox4 is a hallmark of all types of CKD." (PMID 32823917, 2020). "In a streptozotocin (STZ)-induced type 1 diabetes rodent model, increased expression of Nox4 is associated with ROS-induced kidney damage, while Nox4 knockout can protect STZ-induced diabetic mice against glomerular injury." (PMID 29088780, 2017). "This is indicated by improved urine markers of kidney damage, the results from the urine metabolomics study, the normalization of mitochondrial protein levels, and the reduction of renal NOX4 expression, MDA levels, and urinary fumarate." (PMID 37047807, 2023). "These indicated that Nox4 and H2O2 are triggered during nephropathy caused by AOPPs-RSA by PRR-dependent mechanisms." (PMID 37049779, 2023). "Dex is possible to inhibit the expression of α-SMA and renal fibrous substance deposition in rat kidney via RhoA/ROCK/Nox4 signaling pathway, thereby reducing early kidney damage in model rats." (PMID 31844679, 2019). "Results of PAS staining indicate that lentivirus-mediated knockdown of Nox4 significantly attenuated cisplatin-induced kidney damage." (PMID 27999546, 2016). "Ziying Wang, etc. showed that the NOX4 -derived ROS up-regulates TRPC6 expression in puromyc in aminonucleoside-induced nephropathy, which subsequently regulates the intracellular calcium homeostasis." (PMID 25203114, 2014). "Although we did not directly examine inflammation markers, CMS121 may also protect against kidney damage in db/db mice by acting as an anti-inflammatory agent as suggested by the effects of CMS121 on kidney NOX4 levels." (PMID 37047807, 2023). "As a consequence, the PRR might be able to regulate Nox4/H2O2 signaling during AOPP-induced nephropathy in rats." (PMID 37049779, 2023). "Uric acid is a prooxidant molecule that induces kidney damage through the activation of NOX-4." (PMID 33354281, 2020). "In contrast, reduced endothelial Nox4 expression associated with reduced H2O2 production and H2O2-mediated vasodilation may hamper the protective function of Nox4 on the kidneys, thus contributing to kidney damage." (PMID 32823917, 2020). "As noted by the study, PRO20 has also been found to protect against AOPPs-RSA-induced nephropathy by inhibiting the RAS and oxidative stress-related protein Nox4 and H2O2 production." (PMID 37049779, 2023). "Discussion: GL-PP inhibits intrarenal PRR/sPRR-RAS activation and upregulation of NOX4 and H2O2, suggesting potential therapeutic approaches against DOX-induced nephropathy." (PMID 37841924, 2023). "Here, we generated an animal model of DOX-induced kidney damage and examined the effectiveness of GL-PP in reducing proteinuria by inhibiting the RAS and NOX4/ROS signaling pathways." (PMID 37841924, 2023). "Of note, cisplatin significantly increased protein levels of Nox4 both in cisplatin-challenged HK2 cells and cisplatin nephropathy, which was largely blocked by PA treatment." (PMID 27999546, 2016). "In summary, these findings suggest that PRR inhibition may serve as a protective mechanism against AOPP-induced nephropathy by inhibiting the intrarenal RAS and Nox4-derived H2O2 mechanisms." (PMID 37049779, 2023). "Therefore, in this study, we mainly focused on clarifying that NOX4 activates the NLRP3 inflammasome and leads to pyroptosis, which is related to kidney damage in diabetic mice." (PMID 32456088, 2020). "The role of NOX4, but not TRX2 and SIRT3/SOD2 signaling pathway, in UUO and IRI-induced nephropathy has been reported." (PMID 35355864, 2022).
chronic kidney disease (17 papers, 2017 to 2025). Impairment of the renal function secondary to chronic kidney damage persisting for three or more months. "Indoxyl sulfate builds up in the blood of chronic kidney disease patients and triggers the production of superoxide by cells by activating nicotinamide adenine dinucleotide phosphate oxidases (NOX4)." (PMID 40027896, 2025). "Many studies have shown that NOX4-derived ROS represent a key feature of a number of acute and chronic renal diseases." (PMID 41154471, 2025). "Upregulation of Nox4 has been linked to AKI and chronic kidney disease, as well as transforming growth-factor-β-induced profibrotic responses." (PMID 36977025, 2023). "Previous studies suggest the role of oxidative stress produced by NOX1, NOX2, and NOX4 in the vascular smooth muscle cells of chronic kidney disease patients." (PMID 34440716, 2021). "In cardiomyocytes from rodents with chronic kidney disease, soluble klotho has been reported to inhibit ROS generation through the attenuation of Nox2 and Nox4 expression." (PMID 27696667, 2017). "Furthermore, Nox4 is a known source for oxidative stress in many tissues and in chronic kidney disease both Nox4 and oxidative damage markers are increased in muscle." (PMID 32041253, 2020). "Normally, the levels of ROS increase in some AKI and chronic kidney disease (CKD) models, secondary to the overexpression of NOX4." (PMID 35053290, 2022). "In the experimental models of chronic kidney disease (CKD) including DKD, Nox4 expression and activity are increased in the kidney." (PMID 29088780, 2017). "In contrast, other studies suggest that NOX4 expression levels were down rather than upregulated in tubular epithelial cells in chronic kidney disease (CKD), as well as other reports showing a protective effect of NOX4 in the vasculature after ischemia-induced or inflammatory injury." (PMID 33322614, 2020).
diabetic retinopathy (14 papers, 2012 to 2026). "Inhibition of Nox1/4 in bovine endothelial cells reduces the high glucose induced oxidative stress, angiogenic and inflammatory markers, indicated the potential of Nox1 and Nox4 inhibition in reducing the vision damage associated with diabetic retinopathy." (PMID 34571964, 2021). "This genome‐wide association study of severe diabetic retinopathy suggests new evidence for the involvement of the NOX4 gene." (PMID 30178632, 2018). "Moreover, a recent genome wide association study has demonstrated the association of the Nox4 gene with severe diabetic retinopathy in type 2 diabetes patients." (PMID 31277234, 2019). "Nox4 may be an attractive therapeutic target for diabetic retinopathy caused by intensive insulin treatment." (PMID 23144758, 2012). "NOX2, NOX4, and NOX5 have already been associated with the development of retinal vasculopathy in diabetic retinopathy and are also known to be expressed in human endothelial cells." (PMID 36829947, 2023). "By directly inhibiting NOX4 activity, selective inhibitors can prevent pathological ROS generation linked to diseases like diabetic retinopathy, without disrupting physiological ROS signaling." (PMID 41562694, 2026). "Further studies are warranted to elucidate the mechanism of Nox4-induced vascular leakage by investigating other intercellular junctional proteins in endothelial cells and their implications in the pathophysiology of diabetic retinopathy." (PMID 38748682, 2024). "miRNA miR-590-3p, which has been proved to play an active role in inflammation, could directly target NLRP1 and NOX4 and inhibit pyroptosis in diabetic retinopathy through the NOX4/ROS/TXNIP/NLRP3 pathway." (PMID 35957838, 2022). "In cellular experiments in diabetic retinopathy, overexpression of miR-590-3p was found to downregulate caspase-1-dependent pyroptosis via downregulation of NLRP1 and downstream NADPH oxidase 4 (NOX4) pathway." (PMID 35937897, 2022).
ovarian carcinoma (14 papers, 2014 to 2025). A malignant neoplasm originating from the surface ovarian epithelium. "In the present study, JI017 was found to cause ER stress-related apoptosis by activating Nox4-driven ROS formation in ovarian cancer cells A2780 and OVCAR-3 cells." (PMID 34830138, 2021). "Nonetheless, previous studies have demonstrated that NOX2 and NOX4 are frequently upregulated in ovarian cancer and play pivotal roles in tumor progression, chemoresistance, and redox homeostasis." (PMID 40722951, 2025). "An analysis of TCGA transcriptomic data revealed high expression levels of NOX2 and NOX4 in ovarian cancer tissues, with significantly greater expression in tumor samples compared to normal ovarian tissues." (PMID 40722951, 2025). "For example, NOX4 overexpression has been correlated with enhanced ROS production, epithelial-to-mesenchymal transition, and poor clinical outcomes in ovarian cancer patients." (PMID 40722951, 2025). "6-shogaol induces cell death and ER stress-related markers, such as GRP78, p-PERK, p-eIF2α, ATF4, and CHOP, via the upregulation of Nox4, and ROS and intracellular Ca2+ release in ovarian cancer cells." (PMID 36768961, 2023). "The knockdown of Nox4 in ovarian cancer cells inhibits ER stress and cell death by blocking the reduction in cell viability and the enhancement of LDH cytotoxicity, caspase-3 activity, Ca2+, and ROS release." (PMID 36768961, 2023). "Previously, we revealed that ROS induced HER2 and HER3 expression in ovarian cancer cells; here, we found that NOX4 knockdown decreased the expression level of HER3, suggesting that NOX4 regulated drug resistance through HER3." (PMID 34209278, 2021). "The high NOX4 expression predicted the worst clinical outcome in terms of overall survival in patients with endometrial and ovarian cancer." (PMID 34885171, 2021). "In this study, we detected the expression levels of NOX4 in six pairs of human ovarian cancer tissues and adjacent normal tissues." (PMID 34209278, 2021). "NADPH oxidase 4 (NOX4) was responsible for higher NADPH activity to increase ROS production, and NOX4 mRNA levels were much higher in ovarian cancer cells than those in normal cells." (PMID 34209278, 2021). "Taken together, we identified a new HIF-1α/NOX4 signal pathway which induced drug and radiation resistance in ovarian cancer." (PMID 34209278, 2021). "We identified that JI017 causes apoptosis via the PERK–ATF4–CHOP axis and Ca2+ release and induces ER stress and apoptosis by releasing Nox4 and ROS in ovarian cancer cells." (PMID 34830138, 2021). "In ovarian cancer cells, NOX4 knockdown increased sensitivity of targeted therapy and radiotherapy through decreased expression of HER3 and NF-κB p65." (PMID 34930338, 2021). "In this study, we showed that higher levels of NOX4 were detected in a large portion of human ovarian cancer samples." (PMID 34209278, 2021). "Correspondingly, depletion of NOX1 and NOX4 significantly rescued the growth inhibition of tumors formed by PARP1-depleted ovarian cancer cells." (PMID 29684820, 2018). "Our monoclonal antibody confirmed that COV362 ovarian cancer cells clearly demonstrate expression of NOX4 enzyme; expression of its necessary activity partner p22phox was also validated." (PMID 28578276, 2017). "Nox4 knockdown in ovarian cancer cells decreased the levels of VEGF and HIF-1A and tumor angiogenesis." (PMID 24868315, 2014). "Taken together, although further experimental validation (e.g., isoform-specific knockdown) is required, our findings and the existing literature suggest that NOX2 and NOX4 are likely contributors to the ROS-mediated apoptotic effects of hydnocarpin in ovarian cancer cells." (PMID 40722951, 2025). "NOX4 also mediates the resistance to chemotherapy and radiotherapy in ovarian cancer cells." (PMID 35646942, 2022). "Furthermore, we demonstrated that NOX4 played a pivotal role in targeted therapy and radiotherapy resistance in ovarian cancer cells." (PMID 34209278, 2021).
ovarian carcinoma (continued). "Furthermore, knockout HIF-1α by CRISPR-cas9 resulted in significant downregulation of NOX4 in A2780 ovarian cancer cells." (PMID 34209278, 2021). "Therefore, we developed a novel complex herbal medicine, JI017, which mediates endoplasmic reticulum (ER) stress and apoptosis through the Nox4–PERK–CHOP signaling pathway in ovarian cancer cells." (PMID 34830138, 2021). "We reported that ovarian cancer cells had higher expression levels of NOX4." (PMID 34209278, 2021). "Moreover, HIF-1α knockdown also greatly increased radiation sensitivity, indicating that HIF-1α was an effector of NOX4 for mediating radiation resistance in ovarian cancer cells." (PMID 34209278, 2021). "In addition, the knockdown of this gene in ovarian cancer cells has increased the sensitivity to chemo- and radiotherapy, which suggests a key role of NOX4 in the development of drug resistance." (PMID 34885171, 2021). "Taken together, these results indicated that NOX4 may be a novel prognostic marker and therapeutic target for ovarian cancer." (PMID 34209278, 2021). "However, the molecular mechanisms leading to higher levels of NOX4 in ovarian cancer cells remain to be elucidated." (PMID 34209278, 2021). "Furthermore, our results indicated that NOX4 played a pivotal role in chemotherapy and radiotherapy resistance in ovarian cancer cells." (PMID 34209278, 2021). "At the range of physiologically relevant concentrations, IGF-1 markedly induced HIF-1α and NOX4 expression levels in human ovarian cancer A2780 and OVCAR3 cells, thus HIF-1α might be one of the mechanisms regulating the expression level of NOX4." (PMID 34209278, 2021). "In order to investigate whether NOX4 is involved in the targeted therapy resistance of ovarian cancer, we tested whether NOX4 knockdown affected the sensitivity of ovarian cancer to trastuzumab (HER2 inhibitor) treatment." (PMID 34209278, 2021). "Finally, subsequent investigations in ovarian cancer cell lines established that NOX4 protein is localized to perinuclear membranes." (PMID 28578276, 2017). "It is possible that NOX4 may play an underappreciated role in ovarian cancer, an hypothesis supported both by observations of increased NOX4 expression in malignant ovarian tissues and through cell line profiling." (PMID 28578276, 2017). "Moreover, Nox4 has been shown to promote invasion and angiogenesis process in several solid organ tumors, such as renal cell carcinoma, ovarian cancer, and head and neck cancer." (PMID 24868315, 2014). "Therefore, it is interesting to further explore whether NOX4 is involved in the therapy resistance of ovarian cancer cells." (PMID 34209278, 2021). "Therefore, we first investigated whether NOX4 was regulated by HIF-1α in A2780 ovarian cancer cells." (PMID 34209278, 2021). "Detection of NOX4 protein upregulation by low levels of TGF-β1 demonstrated the sensitivity of this new probe; and immunofluorescence experiments found that high levels of endogenous NOX4 expression in ovarian cancer cells were only demonstrable associated with perinuclear membranes." (PMID 28578276, 2017). "In ovarian cancer, the high ROS level, mainly represented by H2O2, due to elevated NOX4 expression, correlated with enhanced angiogenesis and tumor growth." (PMID 39334716, 2024). "We demonstrated that JI017 induces apoptosis via the increase of Nox4, ROS release, caspase-3 activity, LDH cytotoxicity, Ca2+ release, and the decrease of cell viability in the ovarian cancer cell lines, A2780 and OVCAR-3." (PMID 34830138, 2021). "Recently, it has also been shown that, in A2780 ovarian cancer cells, in turn, HIF-1α promotes the production of ROS mediated by NOX4 via an alternative splicing mechanism, emphasizing how this positive feedback process is involved in cancer angiogenesis and tumor progression." (PMID 39334716, 2024).